SLC6A18 (solute carrier family 6 member 18)
Description:
Does not show neutral amino acid transporter activity.
Synonyms: XTRP2; FLJ31236
Tractability: Small molecule: it belongs to a druggable protein family. Antibody: its Gene Ontology location is reachable by antibodies, with high confidence; UniProt predicts a signal peptide or a membrane-spanning region.
Gene: Protein-coding gene on chromosome 5 (1,225,381 to 1,246,189, forward strand). Ensembl gene ENSG00000164363.
Subcellular location: Membrane
Gene Ontology:
Molecular function: amino acid transmembrane transporter activity; transmembrane transporter activity
Biological process: amino acid transport; sodium ion transmembrane transport; renal amino acid absorption
Cellular component: apical plasma membrane; plasma membrane; brush border membrane; membrane
Genetic constraint (gnomAD): Loss-of-function variants: 55 observed, 60.25 expected, observed/expected ratio (o/e) 0.91, 90% interval 0.73 to 1.14. The upper end of that interval is the gene's LOEUF score, 1.14, which puts it in group 5 of 6, group 1 being the genes least tolerant of losing a copy. Missense variants: 790 observed, 846.62 expected, observed/expected ratio (o/e) 0.93, 90% interval 0.88 to 0.99. Synonymous variants: 381 observed, 368.04 expected, observed/expected ratio (o/e) 1.04, 90% interval 0.95 to 1.13.
Homologues: Orthologues: chimpanzee SLC6A18 (89% identical), macaque SLC6A18 (88% identical), rat Slc6a18 (73% identical), mouse Slc6a18 (73% identical), dog SLC6A18 (72% identical), guinea pig SLC6A18 (64% identical), pig SLC6A18 (64% identical), zebrafish slc6a18 (57% identical). Paralogues in human: SLC6A19 (52% identical), SLC6A20 (44% identical), SLC6A15 (40% identical), SLC6A17 (40% identical), SLC6A8 (35% identical), SLC6A12 (35% identical), SLC6A5 (34% identical), SLC6A13 (34% identical), SLC6A9 (34% identical), SLC6A7 (33% identical), SLC6A2 (33% identical), and 6 more.
Diseases named in the same sentence as SLC6A18 in open-access papers:
SLC6A18 is named in the same sentence as 9 diseases in open-access papers, as found by Europe PMC text mining. Sharing a sentence is not in itself a finding about the gene and the disease. The quoted sentences say what the papers report.
Aminoaciduria (1 paper, 2025). An increased concentration of an amino acid in the urine. "The review highlighted 9 genes associated with aminoacidurias, including SLC3A1 (rBAT), SLC7A9 (bo,+AT), SLC6A19 (BoAT1), SLC7A7 (y+LAT1), SLC7A6 (y+LAT2), SLC36A2 (PAT-2), SLC6A20 (SIT-1), SLC6A18 (BoAT3), and SLC1A1 (EAAT3)." (PMID 41142409, 2025).
diabetes (1 paper, 2023). "It is worth noting that the roles of PTPRN2, ASTN2, GRIN1, SLC6A18, and PDE2A in influencing FPG levels or diabetes had previously been suggested." (PMID 37461060, 2023).
glioma (1 paper, 2011). A benign or malignant brain and spinal cord tumor that arises from glial cells (astrocytes, oligodendrocytes, ependymal cells). "Five of the genes, TERT, SLC6A18, CLPTM1L, and CDKN2A/B, have previously been shown to be associated with glioma by other GWA studies." (PMID 21827660, 2011).
iminoglycinuria (1 paper, 2025). A metabolic disorder resulting from defective renal tube reabsorption of proline, hydroxyproline and glycine. "Mutations in genes (SLC36A2, SLC6A20, and SLC6A18) encoding amino acid transporters are responsible for iminoglycinuria." (PMID 41142409, 2025). "In addition, the mutations (957C→G, 1433T→C, 235G→A, and 1486G→A) in the SLC6A18 gene, which encodes for B0AT3, have been documented to be involved in iminoglycinuria (Bröer and Palacin, 2011)." (PMID 41142409, 2025).
lung adenocarcinoma (1 paper, 2015). A carcinoma that arises from the lung and is characterized by the presence of malignant glandular epithelial cells. "CNVs with low amplification (TPPP and SLC6A18) and undefined biological function (LOC100506688) were excluded from further studies on the associations between target CNVs and lung adenocarcinoma prognosis." (PMID 26497366, 2015).
tumor (2 papers, 2020 to 2021). "Conversely, some genes are associated with both tumor status and survival (MUC4 for HNSC, TMPRSS11F, SLC6A18, and DEFB119 for LGG)." (PMID 32625238, 2020).
SLC6A18 also shares sentences with these, for which no sentence is quoted: breast carcinoma (1 paper); depression (1); Hartnup disorder (1).